FAT4 (FAT atypical cadherin 4)
Diseases named in the same sentence as FAT4 in open-access papers (continued):
Sharing a sentence is not in itself a finding about the gene and the disease.
cervical cancer (2 papers, 2023 to 2024). A primary or metastatic malignant neoplasm involving the cervix. "Here, we report the mechanism by which FAT4 overexpression regulates anti-tumor immunity in cervical cancer by inhibiting PD-L1 N-glycosylation and cell membrane localization in a β-catenin-dependent manner." (PMID 37658376, 2023). "According to the Kaplan-Meier survival analysis, cervical cancer patients with low FAT4 expression have a poor prognosis (Logrank P = 0.0036)." (PMID 37658376, 2023). "FAT4 expression was subsequently examined in twelve groups of human cervical cancer tissues and cervical pericarcinomatous tissues (PT), revealing that FAT4 protein levels in cervical cancer tissues were significantly lower than in pericarcinomatous tissues." (PMID 37658376, 2023). "In both normal squamous epithelium tissues and pericarcinomatous tissues, the strong FAT4 immunosignal was found in the cytoplasm and cytomembrane, and FAT4 is low expression in cervical cancer tissues (78% versus 22%)." (PMID 37658376, 2023). "Previous studies have shown that FAT4 inhibits tumor cell proliferation, but its role in cervical cancer is unknown." (PMID 37658376, 2023). "The same methods promote endogenous overexpression of FAT4 in U14 mouse cervical cancer cell lines." (PMID 37658376, 2023). "FAT4 is downregulated in cervical cancer tissues and cell lines." (PMID 37658376, 2023). "Since the molecular weight of FAT4 full-length protein is 543 kDa, we used the deficient Cas9-synergistic activation mediator (dCas9-SAM) technology to transfect ME180 cervical cancer cell lines with short guide RNA (sgRNA) targeting the FAT4 promoter region and endogenously promote FAT4 expression." (PMID 37658376, 2023). "FAT4 expression was first detected in cervical cancer tissues and cell lines." (PMID 37658376, 2023). "Importantly, FAT4 overexpression was able to promote complete tumor regression in C57BL/6 mouse models of cervical cancer, and we collected tumors prior to tumor regression and found that FAT4 overexpression promoted cytotoxic T lymphocyte (CTL) infiltration and activation." (PMID 37658376, 2023). "We first confirmed that FAT4 overexpression binds to β-catenin on the cell membrane in ME180 and U14 cervical cancer cells." (PMID 37658376, 2023). "Finally, we discovered a novel FAT4 protein expression profile in cervical cancer and showed that FAT4 regulates immune editing, suggesting that the FAT4/β-catenin/STT3/PD-L1 signaling axis could be a potential target for cervical cancer." (PMID 37658376, 2023). "To identify the downstream signaling pathways of FAT4-mediated tumor suppression, we performed RNA sequencing on sgFAT4 and non-targeting sgRNA sequence (CTRL) C33A and ME180 human cervical cancer cell lines." (PMID 37658376, 2023).
embryonal carcinoma (2 papers, 2022 to 2025). A non-seminomatous malignant germ cell tumor characterized by the presence of large germ cells with abundant cytoplasm resembling epithelial cells, geographic necrosis, high mitotic activity, and pseudoglandular and pseudopapillary structures formation. "A recent analysis of the Cancer Genome Atlas demonstrated that KIT, KRAS, and NRAS gene variants were observed only in seminoma, while gene variants in B3GNT8, CAPN7, FAT4, GRK1, TACC2, and TRAM1L1 occurred only in embryonal carcinoma." (PMID 41426877, 2025). "Mutations in ADAMTS20, ARHGAP10, OR1L4, PDS5A, and RPLP0 were only found in mixed germ cell tumors, while mutations in B3GNT8, CAPN7, FAT4, GRK1, TACC2 and TRAM1L1 were only observed in embryonal carcinoma, and their mutation frequency was around 2%." (PMID 36713456, 2022). "As described in our results, mutation that only occurs in embryonal carcinoma (B3GNT8, CAPN7, FAT4, GRK1, TACC2 and TRAM1L1) or seminoma (KIT, KARS and NRAS) may be valuable molecular markers and therapeutic targets that need to be considered clinically." (PMID 36713456, 2022). "Differences in somatic mutations between subtypes are also of concern, with our results suggesting that mutations in some genes (B3GNT8, CAPN7, FAT4, GRK1, TACC2, and TRAM1L1) occur only in embryonal carcinoma, while mutations in KIT, KARS, and NRAS are observed only in seminoma." (PMID 36713456, 2022).
esophageal cancer (2 papers, 2016 to 2025). A primary or metastatic malignant neoplasm involving the esophagus. "Consistently, FAT4 gene polymorphisms were reported to be associated with the risks of esophageal cancer and male lung adenoma." (PMID 26672766, 2016).
Intellectual disability (2 papers, 2023 to 2025). "In particular, mutations in the gene encoding SYN1, that we found upregulated in both FAT4 and DCHS1 mutant and KO neurons and hCOs, have been associated with intellectual disability and epilepsy." (PMID 39966398, 2025).
multiple myeloma (2 papers, 2023 to 2024). "However, several associations have not yet been reported, including overexpression of WNK2 in high-grade B-cell lymphoma, of FAT4 in multiple myeloma, and of LRP1B in hairy cell leukemia (HCL), hairy cell leukemia variant (HCL-V), and marginal zone lymphoma (MZL)." (PMID 38769532, 2024).
pancreatic cancer (2 papers, 2012 to 2023). "Using the whole-exome sequencing approach, non-synonymous mutations of human FAT1, FAT3 and FAT4 genes are detected in 1 each, and 2 out of 24 pancreatic cancer samples, respectively." (PMID 23076869, 2012).
Periventricular heterotopia (2 papers, 2022 to 2023). A form of gray matter heterotopia were the mislocalized gray matter is typically located periventricularly, also sometimes called subependymal heterotopia. "FAT4 encodes calcium-dependent cell adhesion proteins, and its genetic variants are involved in recessive syndromes and periventricular neuronal heterotopia." (PMID 36569910, 2022).
squamous cell carcinoma (2 papers, 2023 to 2024). A carcinoma arising from squamous epithelial cells. "The TCGA database was analyzed using the cBioPortal online tools and FAT4 is frequently mutated or deleted in human tumors, especially squamous cell carcinomas, implying that FAT4 dysregulation is a prevalent alteration in human solid tumors." (PMID 37658376, 2023). "Analysis of the TCGA database revealed that the FAT4 gene is mutated or deleted in multiple squamous cell carcinomas, suggesting that FAT4 mutations may be responsible for dysregulation of the Wnt signaling." (PMID 37658376, 2023).
acinar cell carcinoma (1 paper, 2015). "Then, we performed target sequencing analyses for the entire coding regions of BRCA1, BRCA2, FAT1, and FAT4 via a semiconductor sequencer in an additional 4 cases of acinar cell carcinoma, using archival formalin-fixed and paraffin-embedded (FFPE) tissues." (PMID 25743105, 2015).
adrenocortical cancer (1 paper, 2024). "FAT4 is suppressed in various cancer types such as esophageal, gastric, breast, colorectal, liver, and adrenocortical cancer." (PMID 39409043, 2024).
B-cell acute lymphocytic leukemia (1 paper, 2014). "Upstream Hippo inputs have also been found to have hypermethylated promoters with reduced gene expression, including FAT4 in breast cancer and KIBRA and FAT1 in B-cell acute lymphocytic leukemia (B-ALL)." (PMID 25097728, 2014).
bladder tumors (1 paper, 2019). "Specifically, higher rates of FAT4 mutation and MACF1 mutation in bladder tumors with high risk score were found compared with tumors with low risk score." (PMID 31737111, 2019). "Higher rates of FAT4 mutation and MACF1 mutation in bladder tumors with high risk score were found compared with tumors with low risk score." (PMID 31737111, 2019). "Moreover, we also revealed higher mutation rates of FAT4 and MACF1 in bladder tumors with higher risk score." (PMID 31737111, 2019).
bladder urothelial carcinoma (1 paper, 2023). "Patients with bladder urothelial carcinoma and thyroid carcinoma with upregulated FAT4 had a good prognosis, whereas patients with kidney renal clear cell carcinoma with downregulated FAT4 had a poor prognosis." (PMID 37735184, 2023).
Burkitt lymphoma (1 paper, 2025). A rare form of malignant mature B-cell non-Hodgkin lymphoma.
central nervous system lymphoma (1 paper, 2023). "Notably, the prognostic impact of FAT4 has never been reported in hematologic tumors but it was recurrently mutated in primary central nervous system lymphoma, gastrointestinal DLBCL, and splenic marginal zone lymphoma." (PMID 36811800, 2023).
cervical squamous cell carcinoma (1 paper, 2023). A squamous cell carcinoma arising from the cervical epithelium. "Further analysis of the Cervical squamous cell carcinoma and endocervical adenocarcinoma (CESC) dataset revealed that FAT4 mRNA levels were significantly lower in tumor samples than in normal tissues." (PMID 37658376, 2023).
coloboma (1 paper, 2019). An abnormality in which a part of a structure in one or both eyes is missing. "Unlike Fat1−/− mice, no developmental defects, including microphthalmia or coloboma were observed in Fat4−/− mice eyes by E12.5 (n = 20)." (PMID 30862798, 2019).
colorectal tumors (1 paper, 2022). "In colorectal tumors, FAT4 was described as a novel recurrently mutated gene (prevalence of 14%), and more recently, it was also implicated in the regulation of the PI3K/AKT signaling pathway, inhibiting the epithelial-to-mesenchymal transition in CRC cells." (PMID 35392220, 2022).
endometrioid endometrial carcinoma (1 paper, 2022).
Fanconi Anaemia (1 paper, 2022). "These include variants in genes encoding FANCE, a subunit of the Fanconi Anaemia (FA) nuclear complex; NKX2-1, a transcription factor and negative regulator of the NF-κB signalling pathway; and other recognized oncogenes JAK2, PRDM16, BMPR1A and tumor-suppressor genes KMT2C, FAT4, and LRP1B." (PMID 35954343, 2022).
Gorlin syndrome (1 paper, 2017). "Thus, mutations in FAT4 and WNT9b may also play a supporting role in the development of Gorlin syndrome." (PMID 28915250, 2017).
head and neck squamous cell carcinoma (1 paper, 2012). A squamous cell carcinoma that arises from any of the following anatomic sites: lip and oral cavity, nasal cavity, paranasal sinuses, pharynx, larynx, and salivary glands. "Non-synonymous mutations of human FAT2 and FAT4 genes are detected in 1 and 2 out of 32 cases of head and neck squamous cell carcinoma (HNSCC), respectively." (PMID 23076869, 2012).
heart hypertrophy (1 paper, 2017). "The early marker of heart hypertrophy, Nppb24, was strikingly increased (11-fold) in Fat4−/− mutant hearts, whereas the marker of wall stress, Nppa, was not." (PMID 28239148, 2017).
hereditary cancer syndromes (1 paper, 2021). "Among them, APC, FAT4, CTNND1 and TLR2 seem to be the most promising genes because of their role in hereditary cancer syndromes, tumor suppression, cell adhesion and Helicobacter pylori recognition, respectively." (PMID 33525650, 2021).
human papillomavirus infection (1 paper, 2022). "The corresponding barplot of KEGG indicated that the role of FAT4 in the pathogenesis of cancer may be related to human papillomavirus infection, Hippo signaling pathway, PI3K–Akt signaling pathway." (PMID 36051999, 2022).
liver cancer (1 paper, 2019). An epithelial or non-epithelial malignant neoplasm that arises from the liver. "Non-synonymous mutations that result in amino acid coding change in FAT4 have been reported in several cancers including colon, gastric, esophageal and liver cancers." (PMID 31395065, 2019). "The FAT4 mRNA expression levels were also significantly reduced in the four liver cancer cell-lines (Hep3B, HepG2, HepG2.2.15 and Huh7) compared with the normal cell-line L02 (P < 0.001)." (PMID 31395065, 2019).
Lymphatic Metastasis (1 paper, 2018). Transfer of a neoplasm from its primary site to lymph nodes or to distant parts of the body by way of the lymphatic system. "FAT4 expression reduced from 75.9% to 32.4% in the patients with lymphatic metastasis with increasing N grades (N0 to N4 grades)." (PMID 29435168, 2018). "FAT4 methylation gradually increased from 14.0% to 53.8% in patients with lymphatic metastasis (N0 to N4) and from 7.1% (TNM Grade I) to 34.6% (TNM Grade IV, P<0.05)." (PMID 29435168, 2018).
metastasis (1 paper, 2023). The spread or migration of cancer cells from one part of the body (where they first appeared) to another.
Obesity (1 paper, 2021). Accumulation of substantial excess body fat. "To test these hypotheses in an independent cohort, we interrogated very rare variants (MAF < 0.025%) in TAOK2, DCHS1, and FAT4 in approximately 50,000 exomes from UK Biobank using a case–control approach for severe obesity (n = 925 cases, BMI > 40 kg/m2; n = 46,673 controls, BMI ≤ 40 kg/m2)." (PMID 34748544, 2021).
oral cancer (1 paper, 2022).
ovarian tumors (1 paper, 2020). "Analysis of FAT4 expression in 426 ovarian tumors and 87 non-malignant samples from TCGA and GEPIA public databases revealed that FAT4 expression was lower in ovarian tumors than in healthy tissues, which is consistent with our findings." (PMID 32366234, 2020).
rectal cancer (1 paper, 2022). A primary or metastatic malignant neoplasm that affects the rectum. "FAT4 is a tumor suppressor, and previous studies have shown that FAT4 inhibits EMT and the proliferation of gastric and rectal cancer cells." (PMID 35132327, 2022).
subependymal nodular heterotopia (1 paper, 2022). "Subependymal nodular heterotopias have been described in patients with chromosomal rearrangements, as well as associated with intragenic gene mutations (e.g., in FLNA, ARFGEF2, DCHS1, FAT4, ERMARD, and NEDD4L)." (PMID 35585091, 2022).
T-cell lymphomas (1 paper, 2024). "A recent preprint describes FAT4 mutations in 6/49 T-cell lymphomas, including ALCL and PTCL-NOS." (PMID 39478125, 2024).
van Maldergem syndrome 2 (1 paper, 2023). Any van Maldergem syndrome in which the cause of the disease is a mutation in the FAT4 gene. "Mutations in the CCBE1 gene have been associated with Aagenaes (cholestasis-lymphedema) syndrome, and biallelic mutations in the FAT4 gene can cause Van Maldergem syndrome type 2." (PMID 37322437, 2023).
viral hepatitis (1 paper, 2023). An acute or chronic inflammation of the liver parenchyma caused by viruses. "High FAT4 expression was associated with longer PFS in men, women, patients with American Joint Committee on Cancer T1 + T2 tumor categories, patients with vascular invasion, and patients with viral hepatitis." (PMID 37735184, 2023).
tumor (86 papers, 2007 to 2025). "FAT4 is not only involved in regulating cell growth and planar cell polarity but has also been implicated as a tumour suppressor in a variety of tumours." (PMID 40701960, 2025). "FAT4 is abnormally expressed in many tumours due to mutation or deletion, especially in squamous cell carcinoma." (PMID 39735605, 2024). "This differentiation is crucial for determining the functional significance of FAT4 mutation in tumor biology and its potential as a therapeutic target." (PMID 39323626, 2024). "In tumor-infiltrating immune analysis, we have discovered FAT4 mutation to involve more infiltration of CD4 memory-activated T cells, follicular helper T cells, and gamma delta T cells, while less infiltration of naïve B cells and Tregs." (PMID 39323626, 2024). "Our results demonstrated that the sensitivity of 88.9% was the highest using cfDNA to predict the mutation patterns of tumor DNA with FAT4 mutation." (PMID 36779847, 2023). "The sensitivity of the mutation status of cfDNA to predict mutation in tumor samples was highest in FAT4 (88.9%), followed by MACF1 (80%), CDH1 (75%) and PLB1 (75%)." (PMID 36779847, 2023). "All of these confirmed that FAT4 is directly associated with tumor‐infiltrating immune cells in LUAD, suggesting that FAT4 is essential for immune escape and influenced the immune activity in TME of LUAD." (PMID 35770846, 2023). "Lower risk scores were also correlated with higher immunophenotype scores, tumor mutation burden, and mutation rates in significantly mutated genes (e.g., FAT4 and MUC16)." (PMID 36755298, 2023). "Expression and functional analysis indicated downregulation of FAT4 in tumor tissues and loss of FAT4 induced HCC cell growth and proliferation." (PMID 31395065, 2019). "We also mapped our data with top 20 mutated genes in CRC from COSMIC data sets and found FAT1 and FAT4 to be mutated in tumour, whereas distal margin showed the presence of FAT1, KRAS and SMAD4 mutations." (PMID 30950180, 2019). "In the present study, loss of FAT4 expression was associated with poor prognosis, tumor size, invasion depth, vascular invasion, lymph node and distant metastases." (PMID 29435168, 2018). "Lower FAT4 expression was associated with poor prognosis, tumor size and invasion, and lymph node and distant metastases." (PMID 29435168, 2018). "Meanwhile, we depicted the intertumor and intratumor heterogeneity of individual tumors, and identified FAT4 as a recurrently mutated tumor suppressor gene in HCC." (PMID 26672766, 2016). "Clinically, FAT4 mutations were significantly enriched in patients with vascular invasion (P = 0.032) and advanced tumor stages (P = 0.088), and correlated with increased recurrence (P = 0.041)." (PMID 26672766, 2016). "FAT4-low expression associated with larger tumor size (p = 0.041) and advanced tumor stage (P = 0.032)." (PMID 26672766, 2016). "FAT-family proteins, including FAT1, FAT3, and FAT4, were found to be expressed in all examined tumor samples, including those with mutations." (PMID 25743105, 2015). "FAT4 mutations are observed in 21% of S-LUAD tumours but only 3% of NS-LUAD tumours." (PMID 41509216, 2025). "Finally, the molecular mechanisms associated with FAT4 and the ability of FAT4 to regulate tumor-infiltrating cells and affect the prognosis of patients with HCC must be further explored." (PMID 37735184, 2023).